RECQL4 (RecQ like helicase 4)
Diseases named in the same sentence as RECQL4 in open-access papers (continued):
Sharing a sentence is not in itself a finding about the gene and the disease.
glioblastoma (6 papers, 2020 to 2025). The most malignant astrocytic tumor (WHO grade IV). "Overexpression of RECQL4 mRNA and protein levels were also associated with poor survival outcomes in glioblastoma, while silencing of the gene led to significant chemosensitivity." (PMID 35782872, 2022). "We found upregulated RECQL4 expression in highly malignant brain tumours (glioblastomas) associated with poor survival of patients." (PMID 33050631, 2020). "We identified a set of recurrent RECQL4 mutations occurring only in glioblastoma which encompasses several novel, potentially pathogenic variants, for which no relevant information was found in several databases (e.g. National Center for Biotechnology Information, Ensembl, ClinVar)." (PMID 41419455, 2025). "We recently discovered novel mutations in the RECQL4 gene in glioblastoma (GBM), the most malignant brain tumor in adults." (PMID 41419455, 2025). "Increased RECQL4 expression has been reported in many human malignant tumors, including glioblastoma." (PMID 41317405, 2025). "Our results highlight the distinct roles of RecQ helicases in a response to chemotherapeutics and support a rationale for targeting RECQL4 as a therapeutic strategy in glioblastoma." (PMID 41023983, 2025). "A heatmap highlights that four M1 set samples show strikingly different patterns of expressed genes in comparison to the wild type (WT) RECQL4 glioblastoma samples or normal brains (NB)." (PMID 41419455, 2025). "Studies show higher RECQL4 expression was observed in glioblastoma stem cells, whose development was impaired upon RECQL4 inhibition." (PMID 35782872, 2022). "RECQL4 deficiency affected mitochondrial network and reduced mitochondrial membrane polarization in LN18 glioblastoma cells." (PMID 33050631, 2020). "We found RECQL4 both in the cytosolic and mitochondrial fractions of U87-MG, LN18 glioblastoma cells, WG4 and IPIN patient-derived cultures by Western blotting." (PMID 33050631, 2020).
Immunodeficiency (6 papers, 2010 to 2025). Failure of the immune system to protect the body adequately from infection, due to the absence or insufficiency of some component process or substance. "We suggest screening children with RECQL4 mutations for immunodeficiency and stress the need for further research into its physiopathology." (PMID 26064716, 2015). "With this report, we aim to stress the importance of screening immunodeficiency in patients with RECQL4 mutations for immunodeficiency and the need to further research into its physiopathology." (PMID 26064716, 2015). "The pathophysiology of immune deficiency in RTS with RECQL4 mutations can probably be seen in the context of the multiple roles of RECQL4 in DNA metabolism, as summarized above." (PMID 21143835, 2010). "Most patients reported with significant immune deficiency did have RECQL4 mutations." (PMID 21143835, 2010).
melanoma (6 papers, 2012 to 2025). A malignant, usually aggressive tumor composed of atypical, neoplastic melanocytes. "Our data have clearly identified an association of RECQL4 with disease progression and shorter survival in melanoma patients." (PMID 39812592, 2025). "Similar to the SNP-based findings, the RECQL4 region had the strongest association with the risk of melanoma (gene-based P-value = 2.5×10−3) and the RTEL1 region had the strongest association with risk of dysplastic nevi (gene-based P-value = 0.004)." (PMID 23300679, 2012). "The C allele of the SNP rs2721173, located in the gene region RecQ protein-like 4 (RECQL4), was associated with an increased risk of melanoma (OR = 1.35, 95% CI: 1.13, 1.62; P-trend = 1.13×10−3)." (PMID 23300679, 2012). "Furthermore, high RECQL4 amplification was consistently associated with shorter OS across different melanoma histological subtypes (cutaneous, mucosal and uveal melanoma)." (PMID 39812592, 2025). "Now, using RNA‐seq, whole exome sequencing and clinical data from cancer patients, including several already published cohorts of melanoma patients under immunotherapy, our data indicate RECQL4 as a potentially ‘druggable’ factor associated with an unfavourable anti‐tumour immune response." (PMID 39812592, 2025). "In contrast, WRN and RECQL4 may have a tumor suppressor function in melanoma since melanoma has been reported in patients with loss of function mutations in these RecQ proteins." (PMID 25538733, 2014). "To elucidate the mechanistic principle of RECQL4's involvement in our observed phenomena and its potential interference with ICI resistance in melanoma, we performed gain and loss of function analyses by generating genetic variants." (PMID 39812592, 2025). "It is therefore imperative to conduct thorough and meticulous research into these issues prior to the introduction of RECQL4 inhibition in melanoma patients undergoing treatment with ICIs." (PMID 39812592, 2025). "Performing germline/tumour whole-exome sequencing of 44 stage III/IV melanoma patients we identified pathogenic germline mutations in CDKN2A, CDK4, ATM, POLH, MRE11A, RECQL4 and XPC, affecting 7/44 patients." (PMID 33077847, 2020). "The gene regions around RECQL4, RTEL1 and TERF2 were associated with melanoma, the presence of dysplastic nevi and number of nevi, respectively, in the Italian combined study." (PMID 23300679, 2012). "Finally, we asked if the immune checkpoint blockade treatment per se is able to induce a shift in RECQL4 expression in melanoma patients." (PMID 39812592, 2025). "Furthermore, the proportion of melanoma samples with high TMB (≥10 mut/Mb) was diminished in the presence of RECQL4 high amplification (p = 1.05e‐11)." (PMID 39812592, 2025). "The subsequent objective was to ascertain whether RECQL4 transcriptional alterations also play a role in melanoma." (PMID 39812592, 2025). "Additionally, our investigation encompassed an examination of the secretome derived from transfected cells in relation to the empty vector control, with the aim of elucidating the influence of secreted factors on the tumour microenvironment of RECQL4‐overexpressing melanomas." (PMID 39812592, 2025). "We evaluated the interplay of ICI response and RECQL4 expression in melanoma cohorts of 95 responders and 85 non‐responders prior to and after ICI‐targeted therapy and tested the prognostic power of RECQL4." (PMID 39812592, 2025). "We identified RECQL4 as a critical negative regulator of poor prognosis and response to ICI therapy, but also demonstrated its suitability as an independent biomarker in melanoma." (PMID 39812592, 2025). "Interestingly, high baseline RECQL4 expression was also predictive of shorter PFS (p = 2.07e‐02) and OS (p = 2.79e‐04) in melanoma patients receiving immune checkpoint‐targeted therapy." (PMID 39812592, 2025).
melanoma (continued). "In conclusion, the collective downregulation of MHC‐II expression and the alteration of immune‐related soluble factors driven by RECQL4 may promote tumour evasion, potentially impairing the efficacy of ICI therapy in melanoma patients." (PMID 39812592, 2025).
bone marrow failure (4 papers, 2015 to 2025). "RECQL4 is essentially involved in DNA-repair and inactivation of this gene resulted in bone marrow failure due to increased apoptotic rates." (PMID 34257800, 2021). "In the hematopoietic system, a rapid fully penetrant bone marrow failure results from the deletion of Recql4." (PMID 25859855, 2015).
breast tumors (4 papers, 2010 to 2022). "An increased RecQL4 mRNA level was also observed in a majority of clinical breast tumor samples examined." (PMID 23894508, 2013). "An increased RecQL4 mRNA level was also observed in a majority of clinical breast tumor samples (38/43) examined." (PMID 23894508, 2013). "Moreover, a markedly increased mRNA level of RecQL4 was identified in breast tumor tissues with the expression being the highest in metastatic tumor samples." (PMID 23894508, 2013). "In this study, we show that most of the human breast tumor cell lines examined display an over representation of 8q24, a chromosomal locus RecQL4 is regionally mapped to, and consequently, a markedly elevated level of RecQL4 expression." (PMID 23894508, 2013). "8q gains and concomitantly, a highly elevated level of RecQL4 protein in breast tumor cell lines." (PMID 23894508, 2013). "Therefore, we asked whether RECQL4 is over-expressed in breast tumors relative to normal tissue." (PMID 36126066, 2022). "Consistent with mBAND-FISH data, RecQL4 band intensity and quantitative real-time PCR result in MDA-MB-231 was very similar to primary HMEC cells, whereas an enrichment of RecQL4 DNA was observed in MCF-10F and other four breast tumor cell lines (MCF-7, MDA-MB361, MDA-MB436 and MDA-MB453 cells)." (PMID 23894508, 2013).
esophageal squamous cell carcinoma (4 papers, 2021 to 2026). Esophageal squamous cell carcinoma (ESCC) is a type of esophageal carcinoma (EC) that can affect any part of the esophagus, but is usually located in the upper or middle third. "First, pan-cancer analysis indicated that RECQL4 was highly expressed in various types of cancers, including LUAD, esophageal squamous cell carcinoma and so on." (PMID 41513625, 2026). "A study analyzed five human lines with esophageal squamous cell carcinoma (ESCC) and found that RECQL4 expression was significantly increased in tumor tissues in contrast to non-tumor tissues." (PMID 35782872, 2022). "RECQL4 can also promote the proliferation, migration and EMT of esophageal squamous cell carcinoma." (PMID 34486474, 2021). "However, whether RECQL4 sustains esophageal squamous cell carcinoma (ESCC) has not been elucidated." (PMID 33628589, 2021).
pancreatic cancer (4 papers, 2021 to 2025). "Analyzing survival by cancer type using the KmPlotter Server showed that increased RECQL4 levels correlated with shorter survival in ovarian, breast, lung, and pancreatic cancer." (PMID 40196015, 2025).
craniosynostosis (3 papers, 2019 to 2023). Craniosynostosis is defined as the premature fusion of one or more cranial sutures leading to secondary distortion of skull shape resulting in skull deformities with a variable presentation. "Previously, hypomorphic variants in genes involved in the regulation of cell division, including CDC45 and RECQL4 (both Green genes) were reported in patients with craniosynostosis." (PMID 36980886, 2023). "Craniosynostosis is a distinctive sign of BGS as it has been reported in 82% (9/11) of BGS patients with RECQL4 alterations but in RBS with ESCO2 pathogenic variants only in the 2 patients herein described and in 2 patients of the literature, for whom no details or images are provided." (PMID 31192177, 2019).
malignant glioma (3 papers, 2020 to 2025). A grade III or grade IV glioma arising from the central nervous system. "We show the presence of various mutations in the RECQL4 in malignant gliomas of mesenchymal origin." (PMID 41419455, 2025). "This study aims to investigate how RECQL4 depletion influences the response of malignant gliomas to chemotherapeutics." (PMID 41023983, 2025). "Altogether, we show elevated expression of RECQL4 in malignant gliomas, which confers survival and proliferative advantage to cancer cells." (PMID 33050631, 2020). "We found upregulation of RECQL4 (at mRNA and protein levels) in malignant gliomas and cell lines." (PMID 33050631, 2020).
metastatic tumor (3 papers, 2013 to 2023). "Irrespective of Recql4 status, metastatic tumors were most commonly located in the lung." (PMID 25859855, 2015).
Type 2 Diabetes (3 papers, 2017 to 2022). "RECQL4 was significantly associated with many endocrine (e.g., Type 2 Diabetes, FDR = 4.53e-06), immunological (e.g., Mean corpuscular hemoglobin concentration, FDR = 2.61e-11) and metabolic traits (e.g., Estimated glomerular filtration rate, FDR = 9.86e-06)." (PMID 32680461, 2020).
adenocarcinoma of prostate (2 papers, 2023 to 2025). "Apart from pancreatic adenocarcinoma, prostate adenocarcinoma and thyroid carcinoma, we found a significant upregulation of RECQL4 expression in tumours from 18 out of 21 cancer entities (p < .01)." (PMID 39812592, 2025).
astrocytoma (2 papers, 2021). "Furthermore, sequencing of three subependymal giant cell astrocytoma (SEGA)-like astrocytomas in NF1 mutant patients with ALT and intact ATRX have revealed genetic alterations in RECQL4, Fanconi anemia complementation group genes (FANCD2, FANCF, and FANCG), and SMARCAL1." (PMID 34069193, 2021).
bladder cancer (2 papers, 2020 to 2022). "Another report on 98 patients with bladder cancer showed that mutations in DNA repair genes (CHEK2, ERCC5, GEN1, MLH1, PALB2, RAD50, RAD51B and RECQL4) are associated with an unfavorable cancer prognosis and 22% of patients had a mutation." (PMID 35395863, 2022).
brain tumor (2 papers, 2020 to 2025). "Therefore, targeting RECQL4 in deadly brain tumours could be a new strategy to improve eradication of tumour cells by chemotherapeutics." (PMID 33050631, 2020).
cervical cancer (2 papers, 2013 to 2018). A primary or metastatic malignant neoplasm involving the cervix. "In conclusion our study provides a comprehensive report of the expression profile of all the major MCM genes involved in human DNA replication and RECQL4, an important replisome associated factor in cervical cancer." (PMID 23874974, 2013). "Meanwhile, the overexpression of MCM4, MCM5, MCM6, MCM10 and RECQL4 mRNA has been reported as a poor prognostic indicator in cervical cancer." (PMID 29463213, 2018). "Our data indicates the role of MCM4, MCM5, MCM6, MCM10 and RECQL4 in the progression of cervical cancer." (PMID 23874974, 2013). "MCM2, 4, 5, 6, 7, 10 and RECQL4 are significantly over-expressed in cervical cancer." (PMID 23874974, 2013). "Further studies with precancerous lesions may provide clues as to whether these MCMs and RECQL4 can be therapeutic targets in cervical cancer." (PMID 23874974, 2013).
colon adenocarcinoma (2 papers, 2023 to 2025). "As a member of the RECQ helicase family, RECQL4 exacerbates resistance to oxaliplatin in colon adenocarcinoma via the activation of the PI3K/AKT signaling pathway." (PMID 37516854, 2023). "Moreover, it has been reported that RECQL4 expression is increased in CRC and it exacerbates resistance to oxaliplatin in colon adenocarcinoma via the activation of the PI3K/AKT signaling pathway." (PMID 37516854, 2023).
colon cancer (2 papers, 2021). "MGPT was performed after her colon cancer had negative IHC staining for MSH6, and confirmed a germline mutation in MSH6, while revealing additional mutations in BAP1 and RECQL4 genes." (PMID 33541411, 2021).
Ewing sarcoma (2 papers, 2021 to 2023). A small round cell tumor that lacks morphologic, immunohistochemical, and electron microscopic evidence of neuroectodermal differentiation. "VUS were also detected in NF1 in a patient without clinical symptoms of NF1, BRCA2 in a patient with nephroblastoma, SMARCA4 in a patient with Ewing sarcoma, and SEC23B, a candidate gene for Cowden, in a patient with multiple tumours and an additional pathogenic heterozygous RECQL4 variant." (PMID 37507557, 2023).
Fanconi anemia (2 papers, 2017 to 2018). Fanconi anemia (FA) is a hereditary DNA repair disorder characterized by progressive pancytopenia with bone marrow failure, variable congenital malformations and predisposition to develop hematological or solid tumors. "WES revealed that HMCLs displayed frequent mutations in Fanconi anemia genes (PALB2 [12%], FANCI [12%], FANCA [9%], FANCD2 [9%], BRCA2 [9%]) as well as in helicases (such as RECQL4, 15%, and BLM, 15%) and epigenetic modifiers (e.g., TET2, 15% and SETD2, 6%)." (PMID 30545397, 2018).
liver cancer (2 papers, 2022 to 2024). An epithelial or non-epithelial malignant neoplasm that arises from the liver. "Our data confirmed that RECQL4 promotes DNA damage repair after liver cancer radiotherapy, mainly by repairing dsDNA." (PMID 38381090, 2024). "We tested the hypothesis that RECQL4 overexpression in mice with liver cancer receiving radiation therapy reduces tumor sensitivity to RT by antagonizing STING‐dependent elimination of cancer cells." (PMID 38381090, 2024).
lung carcinoma (2 papers, 2013 to 2022). "Furthermore, another study showed that a high expression of the BLM gene, a paralog of RECQL4, was associated with poor prognosis in lung cancer." (PMID 36552262, 2022).
neuroblastoma (2 papers, 2021 to 2023). Neuroblastoma (NB) is the most common solid, extracranial childhood tumor. "Another patient, who was diagnosed with neuroblastoma at the age of 3 years (PaedCan09), carried a heterozygous pathogenic variant in RECQL4 (c.1573del, p.(Cys525Alafs*33)), which was inherited from her mother." (PMID 37507557, 2023). "In our cohort, we found a heterozygous RECQL4 variant in a neuroblastoma patient." (PMID 37507557, 2023).
neutropenia (2 papers, 2016 to 2022). A decrease in the number of neutrophils found in the blood. "Because PN is a possible differential diagnosis in the presence of poikiloderma, we sequenced the USB1 gene in all patients with only one or no RECQL4 mutation and in one patient with poikiloderma and neutropenia." (PMID 27247962, 2016).
progeria (2 papers, 2015 to 2019).
promyelocytic leukaemia (2 papers, 2025). "Interestingly, RAD21, a cohesion involved in ALT-associated promyelocytic leukemia body, and RECQL4, a helicase involved in telomeric integrity maintenance, are often amplified in ALT cell lines." (PMID 40725011, 2025).
Rothmund-Thomson syndrome type 2 (2 papers, 2023 to 2026). "Heterozygous variants in recessive genes like RECQL4 which is associated with Rothmund-Thomson syndrome type 2 are another example." (PMID 37507557, 2023). "This case report presents two Ecuadorian patients with Rothmund-Thomson syndrome type 2 (RTS2), an autosomal recessive disorder, who share a RECQL4 variant previously identified in another Ecuadorian patient, supporting the recurrent presence of this variant in the Ecuador population." (PMID 41737240, 2026).
chromosomal instability syndromes (1 paper, 2023). "Despite WES analysis excluded alterations in RECQL4, the RTS2-causative gene, and in genes associated with other RECQ helicase chromosomal instability syndromes, a preliminary analysis of chromosomal instability was performed on LCLs from both sibs and from control individuals." (PMID 36835439, 2023).
cutaneous melanoma (1 paper, 2025). A primary melanoma arising from atypical melanocytes in the skin. "In light of recent research emphasising the critical role of MHC II‐dependent CD4+ T‐cell immunity in combating cutaneous melanoma, we deeper analysed the interplay between RECQL4 and MHC‐II‐associated molecules." (PMID 39812592, 2025).
head and neck cancer (1 paper, 2022). A primary or metastatic malignant neoplasm affecting the head and neck. "Recent studies described the germline variants of CDKN2A, RECQL4, and SDHB in the DNA repair genes associated with a high risk of head and neck cancer in young patients." (PMID 36552033, 2022).
hereditary cancer (1 paper, 2020). Malignant neoplasms occurring in families at a rate greater than that expected by chance and caused by germline mutations in a specific gene. "In addition to mutations associated with risk of hereditary cancer, pathogenic/likely pathogenic mutations were detected in ERCC2 (n = 1), FANCA (n = 1), FANCC (n = 1), HNF1A (n = 1), PRF1 (n = 1) RECQL4 (n = 2), WRN (n = 1), and XPA (n = 1)." (PMID 31963545, 2020).